CIMAP1A (ciliary microtubule associated protein 1A)
Description:
Outer dense fibers are filamentous structures located on the outside of the axoneme in the midpiece and principal piece of the mammalian sperm tail. May help to maintain the passive elastic structures and elastic recoil of the sperm tail.
Synonyms: ODF3; SHIPPO1; TISP50; hSHIPPO; CT135
Tractability: PROTAC: ubiquitination databases record sites on it.
Gene: Protein-coding gene on chromosome 11 (196,761 to 200,261, forward strand). Ensembl gene ENSG00000177947.
Subcellular location: Cytoplasm; Cytoplasm, cytoskeleton, flagellum axoneme
Subcellular location (Human Protein Atlas): End piece; Mid piece; Principal piece
Gene Ontology:
Molecular function: protein binding
Biological process: flagellated sperm motility
Cellular component: cytoplasm; cytoskeleton; outer dense fiber; sperm flagellum
Genetic constraint (gnomAD): Loss-of-function variants: 23 observed, 22.04 expected, observed/expected ratio (o/e) 1.04, 90% interval 0.75 to 1.48. The upper end of that interval is the gene's LOEUF score, 1.48, which puts it in group 6 of 6, group 1 being the genes least tolerant of losing a copy. Missense variants: 370 observed, 325.95 expected, observed/expected ratio (o/e) 1.14, 90% interval 1.04 to 1.24. Synonymous variants: 145 observed, 123.03 expected, observed/expected ratio (o/e) 1.18, 90% interval 1.03 to 1.35.
Homologues: Orthologues: chimpanzee CIMAP1A (99% identical), guinea pig CIMAP1A (94% identical), mouse Cimap1a (94% identical), rabbit CIMAP1A (94% identical), dog CIMAP1A (93% identical), pig CIMAP1A (93% identical), rat Cimap1a (93% identical), macaque CIMAP1A (89% identical). Paralogues in human: CIMAP1B (46% identical), CIMAP1D (35% identical), CIMAP1C (33% identical), STPG2 (22% identical), STPG1 (17% identical).
Diseases named in the same sentence as CIMAP1A in open-access papers:
CIMAP1A is named in the same sentence as 15 diseases in open-access papers, as found by Europe PMC text mining. Sharing a sentence is not in itself a finding about the gene and the disease.
CIMAP1A shares sentences with these, for which no sentence is quoted: infection (3 papers); asthenozoospermia (2); cancer testis (2); tumor (2); acephalic spermatozoa syndrome (1); breast carcinoma (1); cancer (1); chlamydial infection (1); dementia (1); endometritis (1); Fibroadenoma (1); Infertility (1); meningioma (1); proctitis (1); sterility (1).